TMPRSS2 (transmembrane serine protease 2)
Diseases named in the same sentence as TMPRSS2 in open-access papers (continued):
Sharing a sentence is not in itself a finding about the gene and the disease.
cancer (continued). "Given the role of ACE2,TMPRSS2, and TMPRSS4 in providing increased susceptibility to COVID-19in cancer patients, our findings indicate that SLC6A20 might exhibit a similar function." (PMID 37041751, 2023). "Interestingly, about 50% of PCaT samples and derived organoids expressed another cancer marker, TMPRSS2-ERG, in addition to AMACR and EZH2." (PMID 36769153, 2023). "Alongside this observation, TMEM27 expression was found to becorrelated predominantly with ACE2 and TMPRSS2 in pan-cancer samples,supporting the link between SLC6A20 binding proteinTMEM27 and SARS-CoV-2 infection-related proteins, ACE2 and TMPRSS2in different cancer types." (PMID 37041751, 2023). "On the contrary, PTEN alterations, as a primary lesion in cancer, did not display an increased risk for developing TMPRSS2: ERG fusions." (PMID 37185705, 2023). "It has been shown that soluble guanylyl cyclase (sGC) is strongly associated with the TMPRSS2-ERG fusion in clinical PCa cohorts and that the sGC-mediated NO-cGMP pathway is a critical downstream effector of ERG in promoting cancer cell proliferation and tumorigenesis." (PMID 36769153, 2023). "PM2.5-exposure has also been shown to induce an AhR-dependent transcriptional activation of transmembrane serine protease 2 (TMPRSS2) and subsequent expression of the IL-1 family member IL-18 that may promote cancer progression." (PMID 37696458, 2023). "Meanwhile, it is reported that TMPRSS2 was an important factor in cancer development." (PMID 36992839, 2023). "The results obtained from the Oncomine database indicated that relative to normal tissues, the expression level of TMPRSS2 was reduced in many tumour tissues and cancers including breast, bladder, gastric, colorectal, lung, kidney, prostate, ovarian and sarcoma cancer." (PMID 34951103, 2022). "Consistent with the results analyzed from the database, we examined the mRNA expression of the TMPRSS2 gene in human cancer cell lines or tumor tissues of LUAD and BRCA and confirmed that compared with normal cells or tissues, TMADSS2 is highly expressed in LUAD and lowly expressed in BRCA." (PMID 35558557, 2022). "The UALCAN, TIMER and GEPIA were used to further explore the TMPRSS2 expression in various cancers." (PMID 34951103, 2022). "TMPRSS2 manifested the highest level of expression in PRAD than any other cancer tissue." (PMID 36239108, 2022). "In addition, the TMPRSS2 knockout mouse model in the cancer study showed that TMPRSS2 inhibition is safe and effective for molecular therapy of tumours with few on‐target side effects." (PMID 34951103, 2022). "Then, we planned a pan-cancer analysis of TMPRSS2 in malignant tumors." (PMID 35281819, 2022). "UALCAN database was used to verify the level of methylation of TMPRSS2 promoter in various cancers." (PMID 34951103, 2022). "Furthermore, we examined the co‐altered genes with TMPRSS2 for common cancer types and performed functional enrichment analysis." (PMID 34951103, 2022). "Abnormal TMPRSS2 expression indicates that TMPRSS2 may play a role in the progression of these cancers." (PMID 35558557, 2022). "Our study is the first to explore the TCGA database to perform pan-cancer analysis on TMPRSS2." (PMID 35281819, 2022). "In this study, we evaluated the expression of TMPRSS2 that might be responsible for the COVID‐19 condition in patients with different types of cancers." (PMID 34951103, 2022). "Moreover, TMPRSS2 mRNA expression levels in different cancer types were assessed through the Oncomine database." (PMID 35017320, 2022). "Interestingly, we found that TMPRSS2 expression was correlated with diverse immune cell infiltration levels in cancers, especially in LUAD and BRCA." (PMID 35558557, 2022). "This is the first study to demonstrate that the small molecules CD, AD, TQ, and TQFL12 inhibit TMPRSS2 expression, which may have therapeutic roles via targeting TMPRSS2 to prevent SARS-CoV-2 invasion in cancer patients during the COVID-19 pandemic." (PMID 36364238, 2022).
cancer (continued). "However, the correlation of coronavirus disease (COVID‐19) and cancers, and the prognostic value and molecular function of TMPRSS2 in various cancers have not been fully understood." (PMID 34951103, 2022). "TMPRSS2 promoter methylation level was negatively correlated with gene expression level, it is indicated that TMPRSS2 promoter hypermethylation in various cancers may trigger itself and elevates its level accordingly." (PMID 34951103, 2022). "Even though some published studies have validated that overexpressed TMPRSS2-ERG or ERG could promote cancer invasion ability and/or drug resistance, most reports on TMPRSS2-ERG are on the e1e4 form." (PMID 36088396, 2022). "A total of 27 genes or proteins were determined as gene and protein partners of TMPRSS2, which might contribute to regulating the progression of carcinoma mediated by TMPRSS2 and its survival rate." (PMID 34951103, 2022). "As with scientific coincidences, our TMPRSS2 insights are obtained from cancer research." (PMID 34527703, 2021). "CN-sig 5 shows negative association with nearly all cancer genome alteration features excluding TMPRSS2-ETS oncogenic fusions." (PMID 33945534, 2021). "The common TMPRSS2 and FURIN associated genes CTSL, MYC, AKT1, and SRC displayed positive correlations with their corresponding subjects except for the FURIN and MYC correlation in cancers (R 0.012; p 0.199)." (PMID 33796097, 2021). "The mechanisms of ACE2 and TMPRSS2 regulation could be targeted for preventive and therapeutic purposes in the whole population and especially in cancer patients." (PMID 34442770, 2021). "Moreover, the DNA methylation levels of the ACE2 and TMPRSS2 promoters exhibited marked differential changes in cancer samples, indicating a potential modulation of gene expression in KIRC and KIRP." (PMID 34131396, 2021). "Enrichment analysis was performed using HUGO symbols of genes recurrently hit per dataset, indicating that the pathway “Transcriptional misregulation in cancer [KEGG:05202]” was significantly more frequently hit (P = 1.6 × 10−4) within PCa due to TMPRSS2, ERG, ETV1, H3FA3, SLC45A3, and ELK4." (PMID 34891161, 2021). "However, gene expression signatures of PCa with SPOP mutations and TMPRSS2:ERG fusions appeared to be similar, leading to the inference that increased ERG activity was a main oncogenic driver in cancers with SPOP mutations." (PMID 34066106, 2021). "We further analyzed the mutation status of ACE2, TMPRSS2 and IFITM3 in pan-cancers." (PMID 33061814, 2020). "TMPRSS2 (transmembrane protease, serine 2) has also been shown to regulate apoptosis in cancer." (PMID 32730293, 2020). "Survivin loss was significantly more common in cancers carrying TMPRSS2:ERG fusions (61% survivin negative) than in ERG wild‐type cancers (32% survivin negative; P < .0001)." (PMID 31893572, 2020). "Subset analyses in 3776 cancers with and 4722 cancers without TMPRSS2:ERG fusion revealed that associations with tumor phenotype and patient outcome were largely driven by the subset of ERG negative tumors." (PMID 32143573, 2020). "Subset analyses in 2725 cancers with and 3592 cancers without TMPRSS2:ERG fusion revealed that associations with tumor phenotype and patient outcome were largely driven by the subset of ERG negative tumors." (PMID 32677026, 2020). "Subset analyses revealed that all these associations were strongly driven by the fraction of cancers lacking the TMPRSS2:ERG gene fusion." (PMID 32417965, 2020). "Subset analyses in 5,415 cancers with and 4,217 cancers without TMPRSS2:ERG fusion revealed that these associations with tumor phenotype and patient outcome were largely driven by the subset of ERG-negative tumors." (PMID 31903168, 2019). "A subset analysis of revealed that this association was solely driven by cancers harboring TMPRSS2:ERG fusions (12.7% – 34.0%, p<0.0001) but was absent in fusion negative tumors (12.5% – 12.4%, p=0.4249)." (PMID 31557128, 2019).
cancer (continued). "Associations between TMPRSS2 and TMPRSS4 and cancers have been reported." (PMID 27841306, 2016). "TMPRSS2:ERG score was also significantly higher in men with high prostatectomy Gleason score (>6 versus 6) (P = 0.009) and was significantly associated with Gleason score upgrading and significant cancer (P = 0.008 and P = 0.004, resp)." (PMID 26339615, 2015). "However, eight of the TMPRSS2-ERG positive histologically benign samples resided immediately next to samples classified as carcinoma or PIN." (PMID 26294063, 2015). "Furthermore, our understanding of the impairment of apoptosis in TMPRSS2-ERG positive cancer cells is also incomplete." (PMID 24739220, 2014). "High expression of TMPRSS2:Erg in prostate cancers or EWS-Fli1 in Ewing sarcoma causes DNA damages that are potentiated by PARP-1 inhibition and are followed by strong inhibition of cancer progression." (PMID 23405229, 2013). "Notably, EP-AR TMPRSS2/ERG cells formed large malignant tumors, which surrounded the normal murine prostate nodules (black arrowheads)." (PMID 21747944, 2011). "Similarly, while EP cells failed to grow in vivo following orthotopic implantation and EP-AR cells formed discrete nodules, EP-AR TMPRSS2/ERG cells gave rise to large malignant tumors, stressing the synergistic nature of their cooperation." (PMID 21747944, 2011). "ERG1 was one of the genes with increased expression in this G3 cancer cell type, and its expression could result from a gene fusion event placing it under the control of the androgen regulated TMPRSS2." (PMID 21605402, 2011). "Three, cancer cells may result from luminal differentiation of a neoplastic progenitor-like cell type containing genetic alterations such as the TMPRSS2:ERG fusion." (PMID 21605402, 2011). "Interestingly, SPINK1 has recently been shown to be up-regulated, in a mutually exclusive pattern, in a small percentage of TMPRSS2-ERG-negative carcinomas." (PMID 21814574, 2011). "Finally, a list of genes showed overexpression in TMPRSS2-ERG-negative carcinomas but an even more significant fold-increase in TMPRSS2-ERG-positive tumors, suggesting a role in malignant transformation in the prostate that is potentiated by ERG expression." (PMID 21814574, 2011). "As expected, cancers with rearrangements of the ERG gene had fusions to 5′-TMPRSS2 sequences." (PMID 18594527, 2008). "Targeting ACE2 and TMPRSS2 not only has important prospects as a therapeutic strategy against COVID‐19 and other coronaviruses, especially for cancer patients who may change the expression of these proteins due to malignant tumors or treatments." (PMID 40145441, 2025). "However, as more cancers were studied, a lower percentage of TMPRSS2:ETV1 fusions were found compared to TMPRSS2:ERG fusions, suggesting that other 5′ partners might be involved." (PMID 40427154, 2025). "TMPRSS2 is a serine protease whose gene transcription is regulated by testosterone and dihydrotestosterone through stimulation of the androgen receptor; this protein is involved in different physiological and pathological processes, such as cancer and viral infections." (PMID 38254788, 2024). "As such, TMPRSS2 may serve as an important biomarker for the prognosis of patients with cancer." (PMID 37511059, 2023). "TMPRSS2 might play a role in pain experience, especially for cancer patients." (PMID 36830955, 2023). "Moreover, TMPRSS2-ERG fusion can serve as cancer-specific biomarker for early diagnosis of PCa and can be detected in urine samples via reverse transcription–polymerase chain reaction (RT-PCR) or a clinical-grade transcription-mediated amplification (TMA) assay." (PMID 35267426, 2022). "Therefore, we investigated whether the expression levels of TMPRSS2 in different types of cancers were correlated with immune infiltration levels." (PMID 35558557, 2022).
cancer (continued). "In conclusion, the findings of this study demonstrate that TMPRSS2 may be an effective biomarker and therapeutic target in various cancers in humans, and may also provide new directions for specific tumour patients to prevent SARS‐CoV‐2 infection during the COVID‐19 outbreak." (PMID 34951103, 2022). "However, the systematic analysis of TMPRSS2 aberrations in human cancer remains to be elucidated." (PMID 35281819, 2022). "In addition, the prognosis of TMPRSS2 related to immune cells in cancers was analyzed." (PMID 35558557, 2022). "Moreover, mounting experimental and clinical evidence have also suggested a central role for the signaling networks operating to promote a metastatic and/or therapeutic resistance cascade in cancer development that involves interactions of AR, TMPRSS2, HGF and c-MET with critical components of TMEs." (PMID 29587825, 2018). "Novel genetic markers (such as Transmembrane protease serine 2 (TMPRSS2)-ERG fusion gene mRNA) or prostate cancer gene 3 (PCA3) had already entered the clinical practice, raising the question whether subsequent protein changes impact the evolution of the disease and the response to treatment." (PMID 28061466, 2017). "Therefore, the question still remains, if the TMPRSS2:ERG fusion alone is not sufficient to cause cancer, what changes does it induce in prostate epithelial cells to predispose them to become cancerous." (PMID 26310325, 2015). "In addition, TMPRSS2-ERG-transfected EP-AR cells formed large malignant tumors." (PMID 24739220, 2014). "However, dual/complex TMPRSS2:ERG fusion, which has been shown to associate with poor survival, occurs with a substantially greater frequency in Met/CRPC patients (17%) than in primary cancer patients (3%)." (PMID 24098661, 2013). "Personalized approaches considering the specific cancer type, patient hormonal status, and ACE2/TMPRSS2 expression profiles will be critical for optimizing therapeutic outcomes." (PMID 40145441, 2025). "One of the multiparametric tests, the MiPS (Michigan Prostate Score) includes analysis of PCA3, TMPRSS2/ERG and serum PSA to improve detection of high-grade cancers." (PMID 40115018, 2025). "The insights gained from the analysis of TMPRSS2 and ACE2 in the context of COVID‐19 and cancer have significant clinical implications." (PMID 40145441, 2025). "It was shown that TMPRSS2 activates matriptase, a TTSP whose uncontrolled activation contributes to cancer development." (PMID 41408854, 2025). "The altered immunological milieu in cancer patients, characterized by dysregulated cytokine profiles, can modulate the expression of ACE2 and TMPRSS2, further impacting the course of SARS‐CoV‐2 infection." (PMID 40145441, 2025). "Building upon the therapeutic considerations, future research should focus on clinical evaluations of TMPRSS2 inhibitors, ADTs, and ACE2 modulators in cancer patients." (PMID 40145441, 2025). "Kidney cortex samples from patients subjected to cancer nephrectomy (male/female; < 50 years/˃75 years, n = 24; ˃80 years, n = 15) were analyzed for ACE2 and TMPRSS2 protein levels." (PMID 39382598, 2025). "A large biobank of freshly frozen healthy tissue from cancer-nephrectomy from human adult patients allowed quantitative analyses of protein levels for ACE2 and TMPRSS2." (PMID 40631549, 2025). "Most of them measured either cancer-related proteins (i.e., PSMA, PCA3, TMPRSS2:EGR, or PSA) or exosomal cell surface proteins (CD9, CD3, EpCAM, or CD81)." (PMID 39859516, 2025). "On the other hand, genetic and epigenetic modifications common in cancers can impact the expression and function of ACE2 and TMPRSS2." (PMID 40145441, 2025). "Integrating these findings with the hypothetical roles of ACE2, TMPRSS2, and FURIN in cancer development provides a more comprehensive understanding of the potential mechanisms at play." (PMID 39350850, 2024).
cancer (continued). "Biopsy specimen for cancer genome profiling revealed deletion of BRCA 2 and PTEN, AR amplification, and the presence of the TMPRSS2-ERG fusion gene." (PMID 38428891, 2024). "The cancer genome profiling revealed deletion of BRCA 2 and PTEN, AR amplification, and the presence of the TMPRSS2-ERG fusion gene." (PMID 38428891, 2024). "Transmembrane protease serine 2 (TMPRSS2), angiotensin-converting enzyme 2 (ACE-2), and other host cell proteases including cathepsin L, which is frequently expressed in cancer patients, are known to enhance COVID-19 infection." (PMID 36675457, 2023). "We found that the cells of early PCCs and corresponding PDOs expressed epithelial and cancer markers (AMACR, TMPRSS2-ERG, and EZH2)." (PMID 36769153, 2023). "Here, we show systematic profiling of SLC6A20 expressionin pan-cancer tumor and healthy samples together with correlationwith SARS-CoV-2 infection genes ACE2, TMPRSS2, and TMPRSS4 and immunefiltration in tumor samples." (PMID 37041751, 2023). "The expressional levels for ACE2 and NRP1 mRNA occupy first and second position across all cancers analysed for CCRCC and PRCC, whereas TMPRSS2 was more modestly expressed." (PMID 36595529, 2023). "AhR further interacted with the promoter of TMPRSS2, thereby upregulating TMPRSS2 and IL18 expression to promote cancer progression." (PMID 36975376, 2023). "The cells from the prostate tissue, PCCs, and PDOs were assessed for the epithelial basal (CK5, p63) and luminal (CK18, AR1) markers, mesenchymal (vimentin) marker, and cancer (AMACR, TMPRSS2-ERG, and histone methyltransferase EZH2) markers by RT-PCR." (PMID 36769153, 2023). "TMPRSS2, an androgen-regulated gene and a product of repeated ETS gene fusion, is the driver of various cancers, including PC, with a TMPRSS2 gene fusion to ETS transcription factors of 50% in PC." (PMID 37152924, 2023). "This suggests that the levels of ACE2 and TMPRSS2 and the impact of G-CK in RAW 264.7 cells, differ from those observed in cancer cells." (PMID 37809955, 2023). "In fact, a pan-cancer analysis identified that both TMPRSS2 and ACE2 were commonly expressed at low levels in cancers compared with matched individuals." (PMID 35017320, 2022). "Cancer cell lines were treated with small molecules, including cordycepin (CD), adenosine (AD), thymoquinone (TQ), and TQFL12, to mediate TMPRSS2 expression." (PMID 36364238, 2022). "As a result, three genes, SH3BGRL2, TJP3 and TRIM31, were positively correlated with TMPRSS2 and TMPRSS4 for all cancer cell lines and showed distinct differential expression profiles across GI solid tumors." (PMID 35970857, 2022). "Here, the activity of the strain was further explored using human dermal fibroblasts, African green monkey kidney, cancer cell lines (T47D, HCT-8, and A549ACE2/TMPRSS2) and viruses (SARS-CoV-2, HCoV-OC43, and WNV)." (PMID 35622577, 2022). "To start, first different expression patterns of TMPRSS2 and CXCL10 in multidisciplinary cancer types were analyzed using the TIMER database." (PMID 36239108, 2022). "As a cellular protease, transmembrane serine protease 2 (TMPRSS2) plays roles in various physiological and pathological processes, including cancer and viral entry, such as severe acute respiratory syndrome coronavirus 2 (SARS-CoV-2)." (PMID 36364238, 2022). "SOX9 is a critical downstream effector of ERG in TMPRSS2-ERG-positive cancer cells and induces neoplasia and tumor invasion when overexpressed in the murine prostate or cancer cells, respectively, similarly to ERG." (PMID 35267426, 2022). "Cancer cell lines were treated with the small molecules CD, AD, TQ, and TQFL12 to inhibit TMPRSS2 expression in cancer cell lines." (PMID 36364238, 2022). "However, the role of TMPRSS2 in other cancers remains unknown." (PMID 35558557, 2022). "TMPRSS2 is expressed in BRCA, GBM, LGG, LIHC, and other cancer types; the p-value is the highest in LGG." (PMID 36016607, 2022).